CLPP (caseinolytic mitochondrial matrix peptidase proteolytic subunit)
Diseases named in the same sentence as CLPP in open-access papers (continued):
Sharing a sentence is not in itself a finding about the gene and the disease.
infection (continued). "To determine the role of the ClpP subunits in virulence, we used the caterpillar larvae of G. mellonella, an invertebrate infection model that shares many similarities to the mammalian innate immune system and that has been previously shown to be a reliable animal model for B. anthracis Sterne." (PMID 34497598, 2021). "The clpP mutant was significantly outcompeted in all organs during both types of infection, underscoring the central importance of ATP-dependent protein degradation to fitness during infection." (PMID 32461277, 2020). "Moreover, using a murine model of subcutaneous foreign body infection, we also demonstrated that, in the clpP mutant, the increased biofilm formation cannot compensate the other critical ClpP functions missing in the mutant." (PMID 28555174, 2017). "This provided a reliable spatial comparative analysis of two different strains of P. gingivalis and their relationship to a specific organelle (e.g. lysosomes, ER), and further validated the distinct fates of P. gingivalis and its isogenic ClpP- mutant in the primary GECs following 24 h infection." (PMID 21525983, 2011). "Moreover, the histopathology assay results indicated that infection caused by the clpP mutant strain does not cause severe inflammation in mice compared to that of the WT strains." (PMID 37612737, 2023). "However, S. aureus ΔclpP mutant CFU counts in a mouse model 7 days post infection were significantly reduced relative to wildtype S. aureus, suggesting that increased biofilm formation cannot compensate for the reduction in ClpP-mediated bacterial virulence and dissemination in the host." (PMID 36533084, 2022). "As YmoA turnover by the ClpP and Lon proteases is modulated by temperature, it is tempting to speculate that YmoA plays a crucial role adjusting the Csr regulon in response to temperature which is pivotal for the establishment of a successful infection." (PMID 34413840, 2021). "Therefore, we conclude neither ΔclpP1 nor ΔclpP2 is as attenuated as ΔclpX in an animal model of infection and that loss of neither individual clpP subunit by itself is enough to affect virulence." (PMID 34497598, 2021). "Since clpP, lspA, and purB mutants were defective in causing neutrophil lysis and therefore may not overcome neutrophil defenses during infection, we hypothesized these strains would have altered pathogenicity in vivo." (PMID 30766531, 2019). "Heat shock regulation protease gene (clpP), translation elongation factor (tufA) and UDP-galactopyranose mutase synthesis gene (glf) which play important roles in cell surface formation and infection cycle of pathogens were found only in the strain BFF1B1." (PMID 36707682, 2023). "Unlike these Brucella protease components, deletion of the ClpP protein significantly reduced Brucella virulence in both macrophage and mouse infection models." (PMID 37612737, 2023). "Based on these results, we concluded that ClpP positively controls the expression of SaeS L18P in an FtsH and MoeA-dependent manner, and the physiological role of MoeA outweighs its suppressive effect on the SaeRS TCS during infection." (PMID 35481455, 2022). "The clpP mutant was able to mount an overwhelming infection in the absence of neutrophils but not in the presence of neutrophils which suggests neutrophils are key in the control of this strain." (PMID 30766531, 2019).
bacterial infection (3 papers, 2020 to 2022). "Design of small molecules to disrupt the ClpP-mediated proteolytic process is an attractive strategy to treat bacterial infections." (PMID 36463962, 2022). "ClpP is able to regulate several important virulence factors in S. aureus, which are involved in almost every process of bacterial infection of the host, and therefore ClpP is of interest as a novel anti-virulence target." (PMID 35319277, 2022).
hematological malignancies (3 papers, 2021 to 2024). "The implication of ClpP and ClpX in neuronal differentiation and maturation in NB seems contrary to previous studies reporting that ClpXP is overexpressed in hematologic malignancies and solid tumors, and is necessary for the viability of a subset of tumors." (PMID 36675163, 2023).
adenocarcinoma (2 papers, 2021 to 2024). A common cancer characterized by the presence of malignant glandular cells. "All of them were more expressed in adenocarcinoma with the exception of clpP (more expressed in transition tissue) and LpxC‐fabZ (more expressed in non‐neoplastic tissue)." (PMID 37558206, 2024).
vasculopathies (2 papers, 2020 to 2023). "Interestingly, it was observed recently that dysfunctional mitochondria release also toxic mtDNA into the cytosol, thus promoting an SLE-analogous vasculopathy, and indeed excess mtDNA is present in ClpP−/− tissue." (PMID 32342250, 2020).
hematologic cancers (1 paper, 2021). "Unfortunately, the prognostic role of ClpP was not widely studied in different solid and hematologic cancers, there are grounds to state that this topic should be better explored to evaluate whether this protease could be considered a novel prognostic marker." (PMID 34207660, 2021).
intestinal diseases (1 paper, 2023). "In addition, we identified 12 VFs that play a role in the intestinal diseases of giant pandas, including flagella, CsrA, enterobactin, type IV pili, alginate, AcrAB, capsule, T6SS, urease, type 1 fimbriae, polar flagella, allantoin utilization, and ClpP." (PMID 37789855, 2023).
neurodevelopmental disorder (1 paper, 2025). A behavioral and cognitive disorder with onset during the developmental period that involves impaired or aberrant development of intellectual, motor, or social functions. "At the same time, data from genetic and neurodevelopmental disorders caution that ClpP targeting must account for tissue-specific functions." (PMID 41155556, 2025).
CLPP also shares sentences with these, for which no sentence is quoted: endocarditis (3 papers); neuropathy (3); premature ovarian failure (3); acute lymphoblastic leukemia (2); autoimmune disease (2); diffuse midline glioma (2); Hearing impairment (2); leukodystrophy (2); lymphoma (2); microcephaly (2); neurodegenerative disease (2); abscesses (1); Alzheimer disease (1); asthenozoospermia (1); brain ischemia (1); cerebellar ataxia (1); chronic myelogenous leukemia (1); CNS tumors (1); CODAS syndrome (1); colon adenocarcinoma (1); diffuse intrinsic pontine glioma (1); dilated cardiomyopathy (1); female infertility (1); genetic disease (1); Glucose intolerance (1); ischemic cardiomyopathy (1); metabolic disorders (1); mitochondrial disease (1); Mitochondrial myopathy (1); neuroendocrine tumors (1).
A further 7 diseases each share a sentence with CLPP in 1 paper.